ATAD3A (ATPase family AAA domain containing 3A)
Diseases named in the same sentence as ATAD3A in open-access papers (continued):
Sharing a sentence is not in itself a finding about the gene and the disease.
head and neck cancer (3 papers, 2022 to 2023). A primary or metastatic malignant neoplasm affecting the head and neck. "We also examined the expression levels of ATAD3A in human papillomavirus (HPV) negative (−) and positive (+) HNSCC using the gene expression data from TCGA head and neck cancer cohort." (PMID 35093151, 2022).
head and neck squamous cell carcinoma (3 papers, 2022 to 2023). A squamous cell carcinoma that arises from any of the following anatomic sites: lip and oral cavity, nasal cavity, paranasal sinuses, pharynx, larynx, and salivary glands. "highlighted the novel function of ATAD3A in regulating mitochondrial ERK1/2 activation that favors head and neck squamous cell carcinoma development." (PMID 38018291, 2023). "In the present study, we focused primarily on the functional characterization of ATAD3A in head and neck squamous cell carcinoma (HNSCC) and report for the first time that ATAD3A serves as a mitochondrial oncoprotein to drive the development of this deadly disease." (PMID 35093151, 2022). "Combined targeting of ATAD3A and RAS signaling may potentiate anticancer activity for head and neck squamous cell carcinoma therapeutics." (PMID 38018291, 2023).
axonal neuropathy (2 papers, 2017 to 2020). Any nerve disorder affecting the axon of a nerve. "Deletion or mutation of ATAD3A in the WA domain has also been linked to distinct neurological syndromes in humans, including global developmental delay, hypotonia, optic atrophy, axonal neuropathy, and hypertrophic cardiomyopathy." (PMID 33113782, 2020). "Using whole-exome sequencing, another dominantly inherited heterozygous variant c.1064G > A (p.Gly355Asp) in ATAD3A was identified in a mother with hereditary spastic paraplegia and axonal neuropathy." (PMID 33113782, 2020). "A dominant mutation in ATAD3A was later described to cause hereditary spastic paraplegia and axonal neuropathy." (PMID 28549128, 2017).
colon cancer (2 papers, 2019 to 2023). "In breast and colon cancer, ATAD3A forms and stabilizes WASF3 in a complex with endoplasmic protein GRP78." (PMID 31248089, 2019).
liver cancer (2 papers, 2023). An epithelial or non-epithelial malignant neoplasm that arises from the liver. "The role of ATAD3A in the regulation of cholesterol metabolism has been reported in human or mouse steroidogenic cell lines, disease models, and human liver cancer cell lines." (PMID 37569886, 2023). "In addition, we recently showed that, when Huh7 cells, a liver cancer cell line, were overloaded with excessive free cholesterol, total cholesterol levels were substantially higher when ATAD3A was knocked out." (PMID 37569886, 2023). "Interestingly, our recent study showed that the knockout of ATAD3A using Crispr/Cas9 genetic editing in the human liver cancer cell line HuH7 dramatically reduced levels of PINK1, which suggests that ATAD3A interacts with PINK1 differently in different cells." (PMID 37569886, 2023).
lung carcinoma (2 papers, 2020 to 2024). "The highest-ranked genes in both cohorts of primary lung cancers and LC-BrMs included CCNL2, DVL1, ATAD3A, AGRN, and ISG15, where mutation patterns were clustered for the patients." (PMID 39593114, 2024). "Employment of the PKC inhibitor Calphostin C decreases ATAD3A expression, whereas ectopic expression of PKC isozymes increases the expression of ATAD3A in A549 and H23 lung cancer cells." (PMID 33113782, 2020). "Upregulated ATAD3A expression can be induced by serum starvation in lung cancer cells, which is related to the gene’s translation rather than its transcription." (PMID 33113782, 2020). "Although Calphostin C and resveratrol have been reported to inhibit ATAD3A expression in lung cancer cells, these approaches do not directly inhibit ATAD3A; in fact, no specific inhibitors targeting ATAD3A are currently available." (PMID 33113782, 2020).
melanoma (2 papers, 2024 to 2025). A malignant, usually aggressive tumor composed of atypical, neoplastic melanocytes. "In this frame, ATG4D, ATAD3A, and MRPL41 were the top three genes negatively correlated with GALC expression in the TCGA Skin Cutaneous Melanoma database." (PMID 38474307, 2024).
viral infection (2 papers, 2017 to 2020). "Together, these results suggest that ATAD3A and HSPD1 have the ability to promote BmNPV DNA accumulation in viral infection cells." (PMID 28393927, 2017).
adenovirus infection (1 paper, 2024). "In adult mouse cardiomyocytes, those with ATAD3A-expressing adenovirus infection had lower mitochondrial superoxide generation." (PMID 38250153, 2024).
amyloid (1 paper, 2022). "We harvested the brain cortex from mice at 3 months of age, the age at which mice showed enhanced ATAD3A oligomerization but did not exhibit obvious amyloid accumulation or cognitive deficits." (PMID 35236834, 2022).
antineutrophil cytoplasmic antibody associated vasculitis (1 paper, 2025). "The top five biological functions in GWI include childhood-onset systemic lupus erythematosus (SLE), ATAD3A-related type I interferonpathy, SLE, activation of leukocytes, and antineutrophil cytoplasmic antibody associated vasculitis (all p < 0.0001)." (PMID 41337155, 2025).
asthma (1 paper, 2023). "In mice with HDM-induced asthma, ATAD3A protein and mRNA were reduced in the DEK-/- group." (PMID 38274803, 2023). "Additionally, ATAD3A was highly expressed in HDM-induced asthma models and interacted with DRP1, and siATAD3A could down-regulate DRP1 and mtDNA-mediated mitochondrial oxidative damage." (PMID 38274803, 2023). "However, the function of ATAD3A in airway inflammation in asthma is unclear." (PMID 38274803, 2023). "This study is the first to identify a hitherto uncharacterized mechanism, i.e. the DEK/ATAD3A/DRP1 signaling axis, by which DEK promotes PINK1-Parkin mitophagy, NLRP3 inflammasome activation, and aggravates airway inflammation in asthma." (PMID 38274803, 2023). "First, immunofluorescence showed that the co-localization of ATAD3A and mitochondria was enhanced after rmDEK intervention in DEK wild-type mice with HDM-induced asthma, and the co-localization was attenuated after in DEK knockout mice." (PMID 38274803, 2023). "Furthermore, ATAD3A interacted with DRP1 in BEAS-2B cells and lung tissue, and the interaction was more prominent when cells were exposed to rmDEK or in mice with HDM-induced asthma." (PMID 38274803, 2023).
Ataxia (1 paper, 2017). Ataxia refers to impaired coordination of voluntary muscle movement. "That study also identified a homozygous ATAD3A missense mutation in siblings with congenital cataract, ataxia and seizures plus biallelic deletions of ATAD3A and adjacent ATAD3 genes in one subject with severe cerebellar hypoplasia and neonatal death." (PMID 28549128, 2017).
bladder cancer (1 paper, 2023). "In this report, we demonstrated that high ATAD3A expression usually heralds a poor prognosis in bladder cancer patients, and ATAD3A level can be treated as an independent prognostic factor." (PMID 38018291, 2023). "The purpose of this paper was to detect the expression of ATAD3A in BCa and research the relationship between ATAD3A and pathological features of bladder cancer and the prognosis of patients." (PMID 38018291, 2023). "The mean survival time of bladder cancer patients with high ATAD3A expression was shorter than those with low ATAD3A levels." (PMID 38018291, 2023). "ATAD3A can be used as an effective objective index in identifying patients with bladder cancer, which is helpful to judge the patient's condition through its expression level and provide support for optimizing the treatment plan." (PMID 38018291, 2023). "The upregulation of ATAD3A can be used as an effective indicator to diagnose bladder cancer and predict tumor progression." (PMID 38018291, 2023). "In this paper, we investigated the role and possible mechanisms of ATAD3A in bladder cancer development, assessed ATAD3A activation and expression, and compared the expression of this gene in normal bladder tissue and BCa cells." (PMID 38018291, 2023). "By immunohistochemistry, ATAD3A expression was detected in 491 cases of bladder cancer and 110 normal bladder tissues." (PMID 38018291, 2023). "The abnormal overexpression of ATAD3A may be related to the initiation and progress of bladder cancer." (PMID 38018291, 2023). "The expression of ATAD3A in bladder cancer tissues was higher than that in normal bladder mucosa." (PMID 38018291, 2023). "Furthermore, to evaluate the prognostic value of ATAD3A in bladder cancer, we performed a Kaplan–Meier analysis of data from public sources and found that the mean survival time of patients with high ATAD3A expression was significantly shorter than that of patients with low ATAD3A expression." (PMID 38018291, 2023). "Existing studies have fully proved that ATAD3A has a high tumor marker value, but the correlation between its expression level and clinicopathology of bladder cancer is not very clear, and the corresponding research reports are missing." (PMID 38018291, 2023). "Immunohistochemistry was used to detect the ATAD3A protein level in cytoplasm of bladder cancer and nontumor tissues." (PMID 38018291, 2023).
cardiac hypertrophy (1 paper, 2024). "The fact that the SIRT3-ATAD3A axis had positive effects on mitochondrial parameters under the stimulation of pathological cardiac hypertrophy is encouraging and provides support for ATAD3A as a therapeutic target in future research." (PMID 38250153, 2024). "In neonatal rat cardiomyocytes (NRCMs), ISO, a classic stimulus for cardiac hypertrophy, stimulated acetylation of endogenous ATAD3A, similar to NAM and 3-TYP." (PMID 38250153, 2024). "Mechanistically, ATAD3A specifically undergoes acetylation, which reduces self-oligomerization and promotes cardiac hypertrophy." (PMID 38250153, 2024). "Our work uncovers the potential of ATAD3A as a therapeutic target for cardiac hypertrophy." (PMID 38250153, 2024). "Thus, decreased ATAD3A oligomerization under cardiac hypertrophy may result from decreased SIRT3 activity." (PMID 38250153, 2024). "ATAD3A prevents isoproterenol (ISO)-induced mitochondrial calcium accumulation, improving mitochondrial dysfunction and ER stress, which preserves cardiac function and attenuates cardiac hypertrophy." (PMID 38250153, 2024). "Since ATAD3A significantly inhibits mitochondrial oxidative stress and bioenergetics impairment, we explored whether ATAD3A attenuates ISO-induced cardiac hypertrophy." (PMID 38250153, 2024).
cardiomyopathy (1 paper, 2023). A disease of the heart muscle or myocardium proper. "Interestingly, in the case of the dominant A/C chimera causing perinatal lethal cardiomyopathy, markedly decreased complex I activity occurred selectively in cardiac muscle, underlying the importance of the role of ATAD3A in cardiomyocytes." (PMID 37095554, 2023).
Cirrhosis (1 paper, 2022). A chronic disorder of the liver in which liver tissue becomes scarred and is partially replaced by regenerative nodules and fibrotic tissue resulting in loss of liver function. "The results showed that in patients with SS, NASH, and cirrhosis, the expression of ATAD3A in the liver was increased compared to normal." (PMID 35513069, 2022). "To see if this is applied to humans, we stained liver sections from normal individuals and patients with SS, NASH, or cirrhosis with anti-ATAD3A antibody." (PMID 35513069, 2022). "Given that p-mTOR is upregulated in NASH-related cirrhosis and mTOR is regulated by ATAD3A in cow epithelial cells, we expected to see upregulation of ATAD3A during the progression of NAFLD." (PMID 35513069, 2022). "To gain insight into the function of ATAD3A in the progression of NAFLD, we characterized ATAD3A expression in liver samples from rats with NASH along with matching controls and liver specimens from patients with SS, NASH, cirrhosis, or normal tissue." (PMID 35513069, 2022).
cognitive decline (1 paper, 2022). "During the day 5 and day 12 assessments of the Barnes maze test, 8-month-old 5XFADhet;ATAD3A+/+ mice took a longer time and made more errors finding the target escape box than WT and CMV;ATAD3Afl/+ mice, indicating a cognitive decline." (PMID 35236834, 2022).
cognitive deficits (1 paper, 2022). "We hypothesize that ATAD3A oligomerization might cause AD-associated neuropathology and cognitive deficits by suppressing CYP46A1-mediated brain cholesterol metabolism." (PMID 35236834, 2022). "Notably, suppression of ATAD3A oligomerization by either heterozygous knockout or pharmacological inhibition in AD mice enhanced MAM integrity and cholesterol metabolism, suppressed APP processing, mitigated synaptic loss, and ultimately reduced AD-associated neuropathology and cognitive deficits." (PMID 35236834, 2022). "Therefore, inhibition of ATAD3A oligomerization by DA1 reduced the AD neuropathology and cognitive deficits manifested in 5XFAD mice, consistent with our observations made in heterozygous ATAD3A knockout 5XFAD mice." (PMID 35236834, 2022).
colorectal cancer (1 paper, 2025). A primary or metastatic malignant neoplasm that affects the colon or rectum. "Recently, ATAD3A was shown to stabilize GRP78 and thus suppress ER stress in colorectal cancer, contributing to chemoresistance." (PMID 40234890, 2025).
Corneal opacity (1 paper, 2025). A reduction of corneal clarity. "Corneal opacity, reported in seven families, was mainly contributed by variants in ATAD3A." (PMID 39423307, 2025).
COVID-19 (1 paper, 2022). A disease caused by infection with severe acute respiratory syndrome coronavirus 2. "The mitochondrial ATPase family AAA domain containing 3A (ATAD3A) that was upregulated in lymph nodes from COVID-19 autopsy cases; pathogenic variants in ATAD3A have also been linked to type I interferonopathy." (PMID 36143338, 2022).
Encephalopathy (1 paper, 2023). Encephalopathy is a term that means brain disease, damage, or malfunction. "ATAD3A ablation specifically in neurons led to a severe encephalopathy with aberrant cristae due to a loss of the regular ATAD3A interactions with Complex I, LETM1, and PHB." (PMID 36793196, 2023).
fatty liver disease (1 paper, 2023). A reversible condition wherein large vacuoles of triglyceride fat accumulate in liver cells via the process of steatosis. "The important role of ATAD3A in lipid homeostasis also indicates a relationship between ATAD3A and lipid-related diseases such as fatty liver diseases." (PMID 37569886, 2023).
hereditary spastic paraplegia (1 paper, 2022). Hereditary spastic paraplegias (HSP) comprise a genetically and clinically heterogeneous group of neurodegenerative disorders characterized by progressive spasticity and hyperreflexia of the lower limbs. "G355D (substitution of glycine 355 to aspartate) is another WA mutant of ATAD3A representing patients with hereditary spastic paraplegia and tetraplegia." (PMID 35093151, 2022).
influenza (1 paper, 2017). An acute viral infection of the respiratory tract, occurring in isolated cases, in epidemics, or in pandemics; it is caused by serologically different strains of viruses (influenzaviruses) designated A, B, and C, has a 3-day incubation period, and usually lasts for 3 to 10 days. "Next, various deletion mutants of ATAD3A and WASF3 were generated and tagged with C-terminal sequences of c-myc and human influenza hemagglutinin protein, respectively." (PMID 29100377, 2017).
Insulin resistance (1 paper, 2025). Increased resistance towards insulin, that is, diminished effectiveness of insulin in reducing blood glucose levels. "Furthermore, it shows elevated insulin signaling, adipogenesis and adipocytokine signaling pathways, all pointing towards insulin resistance and related to the known ATAD3A effect on fatty-acid metabolism." (PMID 40234890, 2025).
nonalcoholic fatty liver disease (1 paper, 2022). "However, the relationship between ATAD3A and nonalcoholic fatty liver disease (NAFLD) is largely unknown." (PMID 35513069, 2022).
nonalcoholic steatohepatitis (1 paper, 2022). "In this study, we found that ATAD3A was upregulated in the progression of NAFLD in livers from rats with diet-induced nonalcoholic steatohepatitis and in human livers from patients diagnosed with NAFLD." (PMID 35513069, 2022).
oligodendroglioma (1 paper, 2013). A well-differentiated (WHO grade II), diffusely infiltrating neuroglial tumor, typically located in the cerebral hemispheres. "In addition, the under-expression of ATAD3A may be involved in the chemosensitivity of oligodendrogliomas and the transformation pathway." (PMID 24521265, 2013).
pontocerebellar hypoplasia (1 paper, 2017). Pontocerebellar hypoplasias (PCH) are a rare heterogeneous group of diseases characterized by hypoplasia and atrophy and/or early neurodegeneration of the cerebellum and pons. "The identification of five pontocerebellar hypoplasia families with different ethnicities and ATAD3B/ATAD3A gene fusions suggests ATAD3 defects could underlie a significant portion of the remaining cases lacking a molecular diagnosis, especially those with associated cortical abnormalities." (PMID 28549128, 2017).
tongue tumors (1 paper, 2022). "IHC data from mice tongue tumors derived from ATAD3A KO and parental HN12 cells validated that the loss of ATAD3A significantly inhibited ERK1/2 phosphorylation in xenograft tumors." (PMID 35093151, 2022). "Next, we generated orthotopic tongue tumors in mice to evaluate the synergistic effect of salirasib and ATAD3A genetic depletion on tumor growth." (PMID 35093151, 2022).